ACADS (acyl-CoA dehydrogenase short chain)
Diseases named in the same sentence as ACADS in open-access papers (continued):
Sharing a sentence is not in itself a finding about the gene and the disease.
tumor (7 papers, 2019 to 2025). "We also found a reduced tumour mutation burden and frequent microsatellite instability in the low ACADS group." (PMID 39800718, 2025). "The results demonstrated that the tumor of ACADS-deficient mice grew faster and the number of M2 macrophages infiltrating the tumor increased." (PMID 36552870, 2022). "The results demonstrated that ACADS expression diminished both in mRNA and protein levels, and was associated with tumor stage, race, gender, weight, and age." (PMID 34790035, 2021). "Combined with bioinformatics analysis, we hypothesized that the loss of ACADS regulates the metabolism of tumor-associated macrophages and promotes M2 macrophage polarization, resulting in antitumor immunity to promote the occurrence and development of CRC." (PMID 36552870, 2022). "Dimension reduction analysis via the T-SNE method indicated that DCs were enriched in ACADS-OE tumours." (PMID 39800718, 2025). "Using RNA sequencing data from different tumours in The Cancer Genome Atlas database, we observed that ACADS was downregulated and hypermethylated in HCC." (PMID 39800718, 2025). "Immunofluorescence assays were conducted on mouse tumour tissues originating from the NC and ACADS-OE groups." (PMID 39800718, 2025). "The size of the lines indicates the strength of the interactions, highlighting the key communication pathways through which ACADS exerts its effects in the tumor microenvironment." (PMID 41415282, 2025). "Single-cell RNA sequencing (scRNA-seq) was then used to examine TME composition in the NC and ACADS-OE tumours." (PMID 39800718, 2025). "The results of Kaplan–Meier analysis also revealed that HCC patients with high ACADS expression had better overall survival (OS) and tumour-free survival (TFS) than those with low ACADS expression." (PMID 39800718, 2025). "Compared with paired normal tissues, expression levels of ACADS were significantly downregulated in tumor tissues." (PMID 34790035, 2021). "It revealed that ACADS expression in tumor tissues was generally lower than that in normal colon tissues." (PMID 34790035, 2021). "Seven independent datasets containing tumor tissues and normal tissues expression profile were selected for analysis to further verify expression levels of ACADS." (PMID 34790035, 2021). "In consideration of the crucial role of immune infiltration in the pathophysiology of CRC, diverse algorithms were utilized after tumor purity adjustment to analyze correlations between ACADS gene expression levels and immune infiltration." (PMID 34790035, 2021). "In the present study, results from multiple large databases demonstrated that ACADS expression was decreased in CRC tumor tissue in both mRNA and protein levels." (PMID 34790035, 2021). "Our results confirmed that ACADS was decreased in CRC tumor tissue compared with paired normal tissue via multiple databases and systematic bioinformatic tools." (PMID 34790035, 2021). "The UALCAN analysis demonstrated that the methylation level of ACADS in normal tissues was significantly higher than that in tumor tissues." (PMID 34790035, 2021). "The methylation level of ACADS in normal tissues was significantly higher than that in tumor tissues, and several methylation sites were identified." (PMID 34790035, 2021). "Over the course of 35 days, the results of the tumor volume and weight analysis revealed that the ACADS-silenced HCCLM3 cells generated larger subcutaneous xenograft tumors in nude mice as compared to the cells transfected with control shRNA (P<0.05)." (PMID 31652420, 2019). "The TCGA database was then employed to identify tumor tissue samples which showed higher methylation levels at cg01535453, cg08618068, and cg10174836 (which are the target sites of the ACADS CpG islands) as compared with normal liver tissue samples." (PMID 31652420, 2019). "ACADS plays an essential role in activating ICD by upregulating CALR in tumour cells." (PMID 39800718, 2025).
tumor (continued). "Some studies have indicated that ACADS can be epigenetically modified in various tumours." (PMID 39800718, 2025). "The tumour burden was lower in the ACADS-OE group than in the NC group (P < 0.05)." (PMID 39800718, 2025). "Additionally, we separately evaluated the mRNA and protein levels of ACADS in cell and tumour resection samples using RT-qPCR, Western blot and immunohistochemistry (IHC) staining." (PMID 39800718, 2025). "Similarly, MT ACADS MS-2 significantly inhibited the proliferation, migration, and invasion of tumour cells." (PMID 39800718, 2025). "Interestingly, in an HCC mouse model using Hepa1-6 cells, high infiltration of DCs was observed in the ACADS-OE tumours." (PMID 39800718, 2025). "We also observed increased DCs recruitment in tumours with ACADS overexpression." (PMID 39800718, 2025). "HCC transcriptional profiles were also isolated from scRNA-seq of NC or ACADS-OE mouse tumours." (PMID 39800718, 2025). "CALR and ATP (an ICD marker) secretion were both increased in ACADS-OE tumours (P < 0.05)." (PMID 39800718, 2025). "Targeting ACADS may further exert the anti-tumor effect of M1 macrophages, while inhibiting the tumor-promoting effect of M2 macrophages." (PMID 34790035, 2021). "From the TCGA database, we found that the tumor tissues showed higher methylation levels as compared to their normal liver tissue counterparts at the sites cg01535453, cg08618068, and cg10174836 - which are the target sites of the ACADS CpG island." (PMID 31652420, 2019). "Interestingly, increased mRNA levels of these effectors were observed in ACADS-OE tumours." (PMID 39800718, 2025). "The proportion of M2 macrophages in tumor tissue was significantly higher in Balb/cByJ mice than in Balb/c mice, as shown by flow cytometry analysis; this suggested that the deletion of ACADS could induce TAM polarization to M2 macrophages." (PMID 36552870, 2022). "Furthermore, it was noted that tumor growth was modulated in vivo, when ACADS was silenced." (PMID 31652420, 2019). "We further performed IHC on these tumours, and the ACADS-OE tumours had decreased staining intensities of Ki-67, PCNA, and CD34 when compared to NC tumours." (PMID 39800718, 2025). "Combined with the tumour sequencing data obtained from HCC-bearing mice and TCGA, these results suggest that ACADS specifically facilitates CALR expression." (PMID 39800718, 2025). "Our work clarified that ACADS acts as a putative tumour suppressor in HCC and confirmed that a nomogram including ACADS methylation had good predictive performance in HCC." (PMID 39800718, 2025). "The expression levels of ACADL, ACADS, ACADSB, ALDH6A1, ETFDH, and GCDH were found to be lower in tumor samples compared to normal samples, whereas the expression levels of CCNB1 and CDK1 were observed to be higher in tumor than in normal samples." (PMID 37994323, 2023). "We first analyzed the data of each tumor cell line downloaded from the CCLE database, and examined the expression level of ACADS in diverse tumor tissues according to the tissue source." (PMID 34790035, 2021). "The result of EPIC analysis demonstrated that ACADS expression levels were positively related to CD4+ T cells, which might promote CD8+ T cells activation and induce anti-tumor immune responses." (PMID 34790035, 2021). "Increasing the expression level of ACADS will not only help improve the prognosis of CRC patients, but may also lead to enhanced anti-tumor immune responses in CRC patients." (PMID 34790035, 2021). "Expression levels of ACADS in CRC patients were positively correlated with CD8+ T cells, which are activated by interacting with antigens presented through molecules on antigen presenting cells, playing an important role in inducing the anti-tumor immune response." (PMID 34790035, 2021).
autosomal recession disease (1 paper, 2019). "SCAD deficiency, an autosomal recession disease, is caused by the defect of ACADS gene." (PMID 31620161, 2019).
kidney disease (1 paper, 2023). "From the datamining sources through network biology conducted by Cytoscape, it was found that ACADM, CROT, CRAT, and ACADS are the most prominent genes involved in the function of LC and in the pathology of kidney disease." (PMID 36836532, 2023).
ACADS also shares sentences with these, for which no sentence is quoted: cardiac hypertrophy (2 papers); Hyperphenylalaninemia (2); phenylketonuria (2); steatosis (2); 2-methylbutyryl-CoA dehydrogenase deficiency (1); acyl-CoA dehydrogenase deficiency (1); age-related macular degeneration (1); Cirrhosis (1); depression (1); epilepsy (1); genetic disorder (1); glioma (1); glutaric acidemia (1); glutaric aciduria type 2 (1); Hyperinsulinemia (1); Hypertension (1); infection (1); Insulin resistance (1); ischemia (1); lipid storage myopathy (1); melanoma (1); methylmalonic acidemia (1); orotic aciduria (1); preeclampsia (1); schizophrenia (1); scrub typhus (1).